XIST (X inactive specific transcript)
Diseases named in the same sentence as XIST in open-access papers (continued):
Sharing a sentence is not in itself a finding about the gene and the disease.
tumor (continued). "What’s more, the suppression of tumor phenotype by knockdown of lncRNA XIST could be restored by ectopic expression of ZEB1 or inhibition of miR-200b-3p (*P<0.05)." (PMID 28837144, 2017). "We further investigated whether miR-497 mediated the tumor-suppressive effect of XIST knockdown in GC." (PMID 27911852, 2017). "Similarly, knockdown of lncRNA XIST dramatically reduced the tumor incidence from 36.3 to 0% when the mice were injected with 1.0 × 104 cells (group 3)." (PMID 28837144, 2017). "Interestingly, high XIST expression was significantly correlated with tumor size, lymph node metastasis and late TNM stage." (PMID 27911852, 2017). "Expression of XIST and miR-101 in 127 ESCC tumor tissues showed an inverse relation, further confirming that miR-101 may decrease XIST expression in ESCC." (PMID 29100288, 2017). "Previous studies have reported that lncRNA XIST regulates tumor malignancies in several cancers." (PMID 29212233, 2017). "In addition, results from in vivo nude mouse xenograft tumor model showed that XIST knockdown reduced the tumor size, the protein levels of CDK1 and Cyclin D1 in tumors, and increased P21 protein level in tumors." (PMID 29371940, 2017). "Indeed, miR-152 binds to XIST and this miRNA is able to induce anti-tumor effects comparable to XIST downregulation, supporting a ceRNA relationship between miR-152 and XIST in this pathology." (PMID 26992233, 2016). "Furthermore, knockdown of lncRNA XIST exerts its tumor-suppressive effect though down-regulating the expression of EZH2 via miR-101." (PMID 27620004, 2016). "This prompted us to investigate whether knockdown of lncRNA XIST exerted its tumor-suppressive effects through regulating of EZH2 expression." (PMID 27620004, 2016). "Interestingly, in microsatellite stable (MSS) type EAC samples, the expression level of XIST was inversely correlated with the tumor grade (cor = -0.19)." (PMID 25286960, 2014). "Thus, aberrant XIST expression in SUM159 BCCs may serve as nuclear sinks to sequester/antagonize tumor suppressive miRNAs such as let-7a-2-3p to regulate tumor proinflammatory (i.e., IL-6) signaling." (PMID 36922677, 2023). "In addition, these miRNAs could be in turn interacting with lncRNA XIST, which suggested that up-regulation of them might repress XIST expression in tumor cells." (PMID 36212008, 2022). "Thus, miR‐210 would reduce XIST expression and inhibit XIST from acting as a tumour suppressor." (PMID 36116139, 2022). "Importantly, XIST silencing blocked xenograft tumor growth in vivo." (PMID 35899235, 2022). "Furthermore, the tumour weight in the XIST-shRNA1 group was significantly lower." (PMID 36038831, 2022). "Downregulation of XIST in our study may have an anti-tumour effect by regulating miRNA-153-3p/BCL2." (PMID 36038831, 2022). "Additionally, treatment with CuB in the XIST overexpression group suppressed tumor growth." (PMID 34295808, 2021). "Similarly, lncRNA XIST promotes autophagy in RB tumour cells." (PMID 33803216, 2021). "Furthermore, Ki-67 staining revealed that the depletion of XIST suppressed tumor proliferation." (PMID 33364236, 2020). "Moreover, SEs exhibited a significantly lower amount of methylated XIST fragment as compared with NS components (p < 0.0001) and there were also significant differences in the amount of methylated XIST fragment among the various individual tumor subtypes (p < 0.0001)." (PMID 31533343, 2019). "Importantly, some degree of demethylation of XIST promoter was able to be detected in 137 of 146 (93.8%) TGCTs; only nine tumor samples (three SE and six NS, including three mixed tumors, one pure EC, one pure YST, and one pure TE) showed absence of demethylated XIST." (PMID 31533343, 2019). "Therefore, we speculate a competitive relationship between XIST and miR-200c in the regulation of tumour cell occurrence, proliferation and invasion." (PMID 29559853, 2018). "Additionally, the levels of XIST generally varied with tumor size (P<0.05)." (PMID 29752340, 2018).
tumor (continued). "Moreover, knockdown of lncRNA XIST significantly reduced the expression of ZEB1, which was the direct target of miR-200b-3p, and the tumor suppressive effects caused by knockdown of lncRNA XIST could be rescued by re-expression of ZEB1 in CRC cells." (PMID 28837144, 2017). "We investigated whether knockdown of XIST could inhibit tumor growth in vivo." (PMID 27911852, 2017). "Elevated expression of XIST was recently associated with poor survival in CRC patients, and knockdown of XIST inhibited proliferation, invasion, epithelial-mesenchymal transition (EMT) and CRC stem cell formation in vitro, as well as tumor growth and metastasis in vivo." (PMID 29125541, 2017). "Furthermore, the knockdown of the lncRNA XIST could exert tumor-suppressive effects in human GBM stem cells by up-regulating miR-152." (PMID 28293170, 2017). "In addition, we performed IHC to determine whether knockdown of XIST can reduce the expression of Ki-67 and mmp-9 in tissues taken from tumor growth assay in nude mice." (PMID 27620004, 2016). "Moreover, in vivo study also confirmed that knockdown of lncRNA XIST could suppress tumor growth and distant metastasis." (PMID 27620004, 2016). "We next assessed whether the aberrant chromatin status of the Xi also translated into X-linked gene reactivation by assessing XIST together with HDAC8, ATRX, MAGEA6, and TBL1X expression on fresh tumor stamps (including those analyzed above) or tumor-tissue cryosections." (PMID 25653311, 2015). "However, punctate XIST RNA signals beyond the X-chromosome territory could be detected in the tumor cell lines, particularly in ZR-75-1 and MDA-MB-436." (PMID 25653311, 2015). "A number of lncRNAs discussed in previous sections, such as SNHG17, MALAT1, XIST, SBF2-AS1, NKILA, and Linc-pint, have been shown to regulate tumor behavior in preclinical studies through their interaction with the TGFβ pathway." (PMID 41437175, 2025). "Among them, SNHG3 regulates CRC development by regulating proliferation, differentiation and apoptosis, CASC21 regulates CRC development by regulating cell growth, and XIST and NEAT regulate tumor histogenesis and migration by regulating cell migration." (PMID 39830506, 2024). "We classified UM tumor cells into six distinct subclusters based on marker gene expression: C0 WSB1+ TCs, C1 EEF1A1+ TCs, C2 HSPB7+ TCs, C3 XIST+ TCs, C4 GNG11+ TCs, and C5 PCOLCE+ TCs." (PMID 39635521, 2024). "As IL-6 and IL-8 act as key regulators of tumor progression and CSC activity, we focused on IL-6 and IL-8 in this study to determine their roles in mediating XIST regulation of ALDH+ E-CSCs." (PMID 36922677, 2023). "TFs in XIST+ and S100A4+ tumor cells were similar, particularly RUNX3, REL, STAT4, and E2F1, which regulate the EMT process." (PMID 37430270, 2023). "Next, another two trajectory branches, EMT-induced XIST+ tumor cells and invasive and migrative FOSB+ tumor cells, were separated after S100A4+ tumor cells." (PMID 37430270, 2023). "Intriguingly, Li X. and colleagues demonstrated that overexpression of XIST in the TNBC cells MDA-MB-468 and MDA-MB-231 has an anti-tumor effect, leading to cell-growth inhibition." (PMID 37627209, 2023). "In parallel with the most significant inhibition of IL-6 expression in ALDH− bulk tumor cells, miRNA array analysis unveiled that let-7a-2-3p is more robustly upregulated in ALDH− BCCs vs. ALDH+ CSCs following XIST KD." (PMID 36922677, 2023). "The study further indicated that curcumin, a plant component with antineoplastic properties, played an anti-tumor role in RCC by activating the expression of XIST and regulating XIST/miR-106b-5p/p21 axis." (PMID 36969848, 2023). "lncRNA XIST, lncRNA UCA1, and lncRNA AX747207 can also be selectively loaded into exosomes of tumor cells and participate in tumor drug resistance." (PMID 36839784, 2023).
tumor (continued). "As DOX-induced XIST KD markedly abrogates tumor growth and CSC activities across different subtypes of BC, our study also identifies XIST as a potential therapeutic target for CSCs in BC and other malignancies." (PMID 36922677, 2023). "Supporting this abnormal function of XIST in post-XCI tumor cells, XIST expression in a wide variety of cancer cells suppresses or promotes tumor growth and/or metastasis." (PMID 36922677, 2023). "We demonstrate that XIST acts as a master regulator of cytokine-cytokine receptor interactions and drives IL-6 expression from ALDH- bulk tumor cells to regulate ALDH+ CSCs in a paracrine fashion." (PMID 36922677, 2023). "XIST was increased over 150‐fold in RNA‐seq experiments and over 15‐fold in qPCR assays of RNA isolated from PMIS‐miR‐210 cells and tumours." (PMID 36116139, 2022). "Expression of XIST was negatively related to lymph node invasion (P = 0.004) and TNM stage (P = 0.029), but was unrelated to age, tumor size and histopathologic grade." (PMID 36212008, 2022). "Then, functionally similar networks were described involving XIST/miR-155-5p/SOX6, PTEN and XIST/miR-497-59/PDCD4; accordingly, XIST overexpression inhibited tumor growth in vivo." (PMID 35054794, 2022). "XIST knockdown inhibited ARF6, N-cad, GLUT1, and LDHA protein expression and increased E-cad protein expression in tumor tissues." (PMID 35899235, 2022). "Overexpression of XIST suppressed the proliferation, migration, and survival of HCC cells in vitro, and also impeded in vivo tumor development." (PMID 35723009, 2022). "Using qPCR, we analysed the expression of DCN, miR-200c and five lncRNAs (LUCAT1, MALAT1, lncTCF7, XIST, and ZFAS1) in lymph node and liver metastases in comparison to the invasive front and central part of a primary tumour." (PMID 35052821, 2022). "The lncRNA XIST has been verified as an oncogenic gene in non-small cell lung cancer (NSCLC), whereas the tumor suppressors miR-34a, miR-449a, and miR-16 were downregulated in NSCLC." (PMID 35453680, 2022). "Therefore, XIST might function as a tumor suppressor LncRNA by sponging these onco-miRNAs." (PMID 36212008, 2022). "Both RNA‐seq and qPCR of RNA isolated from tumours and transduced SW620 cells demonstrate that PMIS‐miR‐210 inhibits miR‐210 by over 80%, which results in an increase in XIST transcripts." (PMID 36116139, 2022). "Our results demonstrate that the lncRNA XIST is an attractive target of drug development in NSCLC and that favorable outcomes can be achieved through tumor suppressor miRNAs." (PMID 35453680, 2022). "Our present study mainly discovered the downregulation of XIST and MGMT as well as the upregulation of miR-221-3p in HCC cells and tumor specimens." (PMID 35723009, 2022). "Because XIST expression was significantly increased in SW620 cells and tumours expressing PMIS‐miR‐210, we asked if XIST also contributed to epigenetic regulation of NME1." (PMID 36116139, 2022). "We used the PMIS‐miR‐210 system to make stable cell lines and to inhibit tumour growth and identified the NME1 tumour suppressor regulated by an miR‐210/XIST pathway." (PMID 36116139, 2022). "Downregulation of lncRNA XIST activated epithelial-mesenchymal transition, MSN/c-Met, and release of exosomal miR-503, accelerated primary tumor growth as well as metastasis in the brain." (PMID 34707990, 2021). "In order to confirm the effect of XIST on TSCC in vivo, a mouse tumor model in nude mice was established." (PMID 34295808, 2021). "A series of cellular behaviors experiments revealed that overexpression of KCNQ1OT1 or XIST greatly aggravated CRC cell proliferation in vitro and tumor growth in vivo, acting as oncogene in CRC." (PMID 34521445, 2021). "It has been reported that miR-34a influenced tumour biological activities by targeting several genes or signal pathways, such as CCND1 in EC, PDGFR in GC, HMGB1 in CRC, and XIST in PC." (PMID 33446130, 2021).
tumor (continued). "The expression of HYMAI, NEAT1, XIST and FTX were negatively correlated with tumor diameter and significantly down-regulated during GIST progression." (PMID 34557343, 2021). "The lncRNA XIST serves as a miR-34a ceRNA via competing with MET for miR-34a binding and thus promoting cancer cell proliferation and tumor growth through upregulated MET–PI3K–AKT signaling." (PMID 33763422, 2021). "It has also been shown that JPX is lowly expressed in HCC and inhibits HepG2 cell growth or tumorigenesis in a XIST-dependent manner, revealing that JPX has a tumor-suppressing effect in HCC." (PMID 31941509, 2020). "Decreased expression of XIST stimulated EMT and activated c-Met via MSN-mediated protein stabilization, which resulted in the promotion of stemness in the tumor cells." (PMID 31214490, 2019). "Our results showed that suppression of XIST by short hairpin RNA (shRNA) impeded U2OS cell growth, induced apoptosis and lessened OS xenograft tumor growth." (PMID 31189404, 2019). "The study on brain metastasis of BC found that the lncRNA XIST suppressed EMT and the MSN/c-Met axis via MSN-mediated protein stabilization, which leads to the attenuation of stemness in the tumor cells." (PMID 31744046, 2019). "This was consistent with previous reports in which lncRNA XIST was shown to act as a tumor suppressor in BC and with the fact that lncRNA TSIX is a negative regulator of lncRNA XIST." (PMID 31998636, 2019). "Downregulation of XIST activated EMT and stimulated c-Met through stabilizing MSN-mediated protein, which contributed to the activation of tumor cells' stemness." (PMID 31214490, 2019). "Nonetheless, limited evidence displayed lncRNA XIST involvement as a tumor suppressor lncRNA in BC in addition to the absence of concerns regarding lncRNA TSIX, the negative regulator of lncRNA XIST in BC." (PMID 31998636, 2019). "Knockdown of XIST reduced GCS proliferation, migration and invasion as well as tumour growth in nude mice." (PMID 30117678, 2018). "We also highlighted common long non-coding RNA molecules such as HULC, HOTAIR, MALAT1, XIST, H19 and GAS5, which mediate the two-way interactions between stroma and tumor." (PMID 28392501, 2017). "Silence of XIST expression significantly inhibited the proliferation, migration and invasion capacity of ESCC cells in vitro and suppressed tumor growth in vivo." (PMID 29100288, 2017). "XIST induced the upregulation of E2F3 (E2F transcription factor 3), which is a critical protein for tumor cell proliferation." (PMID 29147648, 2017). "Lower XIST expression was observed more frequently in patients with advanced WHO stage (III + IV) (P<0.001) and larger tumor size (≥5, P=0.003)." (PMID 28831025, 2017). "The lentivirus containing LV-sh-contr or LV-sh-XIST was injected into tumor after 5 days of PANC-1 cell injection, and the tumor volume and weight changes on day 5, 10, 15, 20, 25 and 30 were determined in response to XIST knockdown." (PMID 29371940, 2017). "Knockdown of lncRNA XIST remarkably inhibited CRC cell proliferation, invasion, epithelial–mesenchymal transition (EMT) and CRC stem cell formation in vitro as well as tumor growth and metastasis in vivo." (PMID 28837144, 2017). "Knockdown of lncRNA XIST suppressed cell proliferation, invasion, epithelial–mesenchymal transition (EMT) and stem cell formation in vitro as well as tumor growth and metastasis in vivo." (PMID 28837144, 2017). "Interestingly, wo found that XIST, SNHG14, NEAT1, LINC00943, KCNQ1OT1 have pro-tumor functions in various cancers but DHRS4-AS1 can inhibit tumor development." (PMID 40015977, 2025). "Expression of XIST was also increased in both tumor and peritumoral parenchyma samples, albeit without statistical significance (2.10 and 3.60 fold, p=0.41 and 0.36, respectively)." (PMID 39397388, 2025). "Expression of XIST was also increased in both tumor and peritumoral parenchyma samples, albeit without statistical significance (2.10 and 3.60 fold)." (PMID 39397388, 2025).
tumor (continued). "Expression of XIST was also increased in both tumor and peritumoral parenchyma samples, albeit without statistical significance." (PMID 39397388, 2025). "In contrast to nontumor normal tissue samples, tumor samples had a 10-fold lower expression of XIST." (PMID 39546568, 2024). "XIST also binds with the H3K27me3-specific methyltransferase EZH2, a subunit of the polycomb repressive complex 2, and by doing so, it silences the expression of Klf2, a tumor suppressor in non-small cell lung cancer." (PMID 39639337, 2024). "We further explored the methylation of lncRNAs associated with tumor progression through bioinformatics analysis and IGV, and found there was no significant change between CR and relapse samples, such as XIST, MALAT1 and so on (data not shown)." (PMID 37402730, 2023). "Although IL-6 produced from ALDH− bulk tumor cells promotes ALDH+ CSCs in a paracrine fashion, downregulation of IL-6 and upregulation of let-7a-2-3p expression, despite to a lesser extent, were also detected in ALDH+ CSCs upon XIST KD." (PMID 36922677, 2023). "A comprehensive analysis, which included a bioinformatics search, database analysis, and experimental studies on cell lines, allowed for confirming the crucial role of the XIST/miR-520/BAX axis in regulating NSCLC resistance to cisplatin and promoting the ability of tumor cells to avoid apoptosis." (PMID 37686426, 2023). "XIST is variably expressed across the spectrum of BC subtypes, and doxycycline (DOX)-inducible knockdown (KD) of XIST markedly inhibits spheroid/colony forming capacity, tumor growth and tumor-initiating potential." (PMID 36922677, 2023). "Further examination of top 25 downregulated genes in ALDH- vs. ALDH+ cells upon XIST KD identified IL-6 and IL-8 as the top two genes most significantly inhibited in ALDH- bulk tumor cells, and these two cytokine genes are also downregulated, to a lesser extent, in ALDH+ CSCs." (PMID 36922677, 2023). "Some well-studied lncRNAs such as HOX Transcript Antisense RNA (HOTAIR), X-Inactive Specific Transcript (XIST), and Nuclear Enriched Abundant Transcript1 (NEAT1) demonstrated to participate in tumor progression, including regulating cell proliferation, cell cycle, apoptosis, and metastasis." (PMID 36816357, 2023). "As let-7 miRNAs are mainly expressed in bulk tumor cells but not breast CSCs, we propose that XIST-driven IL-6 production from ALDH− bulk tumor cells plays a major role in maintaining ALDH+ CSCs via paracrine IL-6 signaling." (PMID 36922677, 2023). "We also examined the 825 significantly changed genes differentially expressed in ALDH+ CSCs, which identified S100P and S100A9 as the top two genes most significantly inhibited in ALDH+ CSCs but not ALDH- bulk tumor cells upon XIST KD." (PMID 36922677, 2023). "Assessment of the function of X-inactive specific transcript (XIST) revealed that it mainly represses miR-429, a tumor suppressor, and then results in a higher expression of ZEB1 and EMT via the critical axis of XIST/miR-429/ZEB1 and enhances tumor cell invasiveness." (PMID 36402997, 2022). "Their expression was measured in tumor tissues and corresponding non-tumor tissues by quantitative real-time PCR (qRT-PCR), which revealed that XIST was weakly expressed in HCC cells and tumors, while miR-221-3p was overexpressed." (PMID 35723009, 2022). "Therefore, our results support that lncRNA XIST is an attractive target of drug development in tumor growth and aggressive proliferation of NSCLC, and promising results can be achieved through tumor suppressor miRNAs." (PMID 35453680, 2022). "Thus, high levels of miR‐210 expression in SW620 cells reduce XIST transcripts and inhibit NME1 expression to allow for tumour growth." (PMID 36116139, 2022). "We observed that XIST expression was reduced in HCC cells and tumor specimens." (PMID 35723009, 2022).